IL33 (interleukin 33)
Diseases named in the same sentence as IL33 in open-access papers (continued):
Sharing a sentence is not in itself a finding about the gene and the disease.
inflammatory bowel disease (continued). "Furthermore, IL-33 treatment promotes IL-10 production by B-cells in adult mice, thus protecting these mice from induction of inflammatory bowel disease." (PMID 32751234, 2020). "Additionally, a recent report showed that IL-33 is downregulated when its soluble receptor (sST2) is upregulated in the serum of patients with inflammatory bowel disease." (PMID 31849991, 2019). "Indeed, the IL-33/ST2 signaling also played a dichotomous role in inflammatory bowel disease pathogenesis." (PMID 30863362, 2019). "Overall, one cannot rule out the potential role of IL-33 in gut-associated fibrosis, particularly in the setting of turnover of chronic tissue damage and repair, characteristics of inflammatory bowel disease (IBD)." (PMID 30405626, 2018). "It suggested that IL-33 plays a potential role in inflammatory bowel diseases (IBD)." (PMID 26161006, 2015). "Of note, IL-25 and IL-33 have been reported to modulate the severity of various inflammatory diseases involving IL-1β secretion including allergic inflammation, autoimmunity and inflammatory bowel disease." (PMID 23935505, 2013). "Furthermore, IL-33 seems increasingly to be an important cytokine in many inflammatory diseases, such as inflammatory bowel disease, rheumatologic disorders or central nervous system inflammation." (PMID 22349136, 2012). "IL-33 expression was significantly increased in the inflamed mucosa of inflammatory bowel disease (IBD) patients as well as in colitis mice induced by dextran sulphate sodium (DSS)." (PMID 29180837, 2017). "Recently, in the intestinal mucosa, overexpression of IL-33 has been reported in samples from patients with inflammatory bowel diseases (IBD)." (PMID 24701033, 2014). "In 2010, five different research groups consistently described the dysregulation of IL-33 in patients with inflammatory bowel disease (IBD)." (PMID 25032216, 2014). "In 2010, four different research groups consistently described the upregulation of IL-33 in patients with inflammatory bowel disease (IBD)." (PMID 23766561, 2013). "In inflammatory bowel disease (IBD), divergent functions of IL-33 have been depicted." (PMID 30213101, 2018). "Interleukin 33 (IL-33) that signals through the ST2 receptor has emerged as a critical modulator in several inflammatory disorders, including inflammatory bowel disease (IBD)." (PMID 28404987, 2017). "Though the role of IL-33 has been evaluated in gut inflammation (inflammatory bowel disease), its function has not been fully described in human small intestine." (PMID 33133101, 2020). "Moreover, IL-33 could be used as an early marker for ulcer-associated activated fibroblasts and myofibroblast trans-differentiation; thus one cannot rule out its potential role in inflammatory bowel disease-associated fibrosis." (PMID 30405626, 2018). "Dysregulation of ST2/IL-33 signaling and suppression of tumorigenicity 2 (ST2) marker production is observed in various inflammatory diseases such as cardiac disease, inflammatory bowel disease (IBD), graft-versus-host disease (GVHD), and type-2 diabetes." (PMID 35401921, 2022). "IL‐33 performs specialised functions via immune tolerance induction, and the feasibility of IL‐33 has been tested in acute graft‐versus‐host disease (GVHD) and inflammatory bowel disease (IBD), with promising results." (PMID 32566227, 2020). "Recent evidence suggests that the IL-33/IL1RL1 axis plays a critical role in several autoimmune and inflammatory disorders; however, its mechanistic role in inflammatory bowel disease (IBD) has not been clearly defined." (PMID 23634226, 2013).
psoriasis (73 papers, 2013 to 2026). An autoimmune condition characterized by red, well-delineated plaques with silvery scales that are usually on the extensor surfaces and scalp. "The elevated serum concentrations of IL-27, IL-30, and IL-33 have also been observed in psoriasis patients and are significantly associated with disease severity, as determined by the PASI." (PMID 40731810, 2025). "Other DAMPs, such as cytosolic DNA, ATP, self-RNA, the LL37 complex, and IL-33, are also implicated in psoriasis." (PMID 38255845, 2024). "Regarded as both cytokine and damage-associated molecular pattern, IL-33 is released upon keratinocyte damage in psoriasis then activates inflammatory pathways in an autocrine manner." (PMID 37546687, 2023). "Satisfying research results are available indicating a pathogenic link between the IL-33/IL-31 axis and psoriasis and between dysbiosis and psoriasis." (PMID 37509136, 2023). "IL-33, originating from keratinocyte secretion, triggers the expression of psoriasis-associated inflammatory factors and stimulates the progression of skin inflammation in psoriasis." (PMID 38239345, 2023). "MCs are activated by IL-33 in the early stages of psoriasis and exacerbate psoriasis-associated skin inflammation." (PMID 36894987, 2023). "It is well established that activation of the Th1 type of immune response is the hallmark of psoriasis, thus it seems that activation of a pro Th2 response by IL-33 should attenuate psoriasis." (PMID 34884710, 2021). "The activation of MCs by IL-33 causes the release of histamine and cytokines/chemokines, which are very important in rheumatic diseases, including psoriasis." (PMID 34360845, 2021). "In psoriasis, MCs can be activated by IL-1, causing inflammation and triggering a cytokine network including IL-33 and TNF cytokines." (PMID 34360845, 2021). "Data are obtained from the 19 studies identified, which assessed the association between IL-33 and psoriasis." (PMID 31736655, 2019). "Furthermore, the crosstalk between IL-33 and vitamin D plays a key role in the pathogenesis of OP associated with psoriasis." (PMID 39796035, 2024). "Moreover, IL-33 lets DC mature, which enables the induction of differentiation into Th17 cells, producing IL-17A, strongly involved in the pathogenesis of psoriasis, by stimulating keratinocytes into proliferation and causing epidermal thickening." (PMID 38666958, 2024). "This leads to an imbalance of the IL-33–IL-37 axis, involving increased IL-33 and decreased IL-37, which may be associated with the pathogenesis of AD and psoriasis." (PMID 37834081, 2023). "IL-33 has been reported in skin-associated pathologies such as atopic dermatitis and psoriasis." (PMID 34759931, 2021). "Therefore, IL-33 is a cytokine that directly stimulates nerves to cause pruritis and may be related to pruritis in AD and psoriasis." (PMID 37834081, 2023). "Importantly, IL-33 has been associated with skin diseases like psoriasis and contact dermatitis." (PMID 38067128, 2023). "In addition, DCs matured by IL-33 induce differentiation into Th17 cells, which produce large amounts of IL-17A; these in turn increase the proliferative capacity of keratinocytes and cause epidermal thickening in psoriasis." (PMID 37834081, 2023). "It has also been shown that IL-33 released from keratinocytes enhanced the transcription of genes encoding psoriasis-related cytokines, chemokines, and inflammatory molecules in keratinocytes in an autocrine manner, suggesting that IL-33 is also a potential therapeutic target for psoriasis." (PMID 35663970, 2022). "IL-33 exerts immunomodulatory effects by suppressing IL-17A expression in CD4+T cells isolated from psoriasis patients, likely through inhibition of STAT3-dependent IL17A transcription." (PMID 40681996, 2025). "IL-33 can worsen the condition of IMQ psoriasis model mice, reduce CD4 + T and CD8 + T cells in the spleen of psoriatic mice, inhibit autophagy in the skin, and promote STAT3 tyrosine phosphorylation." (PMID 38255845, 2024).
psoriasis (continued). "Firstly, in one study, injecting IL-33 into an imiquimod-induced psoriasis model improved the disease." (PMID 38666958, 2024). "Several studies concluded that the secretion of IL-1, IL-6, and IL-13 by mast cells is activated by IL-33, highlighting its role in psoriasis." (PMID 38666958, 2024). "Studies have proven that patients with moderate-to-severe psoriasis have increased levels of IL-33 in their sera and greater expression intra-epidermally." (PMID 38666958, 2024). "The role of IL-33 in the pathogenesis of psoriasis is exerted via the stimulation of keratinocytes to produce CXCL1 and CXCL8, responsible for recruiting neutrophils and CCL20, which recruits IL-17-producing T cells to the epidermis." (PMID 38666958, 2024). "Interleukin (IL)-31 and IL-33 are both crucial players in the development of AD, and studies are being conducted to elucidate their role in psoriasis." (PMID 37509136, 2023). "To analyse the role of IL-33-MC interaction in psoriasis, we investigated the effect of exogenous IL-33 on the development of IMQ-induced psoriasis under MC-deficient conditions." (PMID 36894987, 2023). "Nevertheless, several studies also observed a significant increase in eosinophils and cytokines, such as IL-4, IL-5, IL-9, IL-31, and IL-33, among others, in the blood of patients with psoriasis." (PMID 36865550, 2023). "The concentration of IL-33 in the serum of AD patients has also been found to be predominantly higher than that of normal subjects and psoriasis patients." (PMID 37834081, 2023). "The aim of this review is to delve into the link between dysbiosis and the IL-33/IL-31 axis in AD and psoriasis, supporting the idea that dysbiosis can act as an aetiological culprit in the development of skin conditions through immunodysregulation." (PMID 37509136, 2023). "In AD and psoriasis, there is an imbalance of the IL-33–IL-37 axis, and pathogenesis is likely to occur via increased IL-33 and decreased IL-37." (PMID 37834081, 2023). "IL-33 expression has been found in the nuclei of keratinocytes in skin lesions of psoriasis patients." (PMID 37834081, 2023). "IL-33 is increased and co-localized with MCs in the dermis of psoriasis-like lesions using immunofluorescence." (PMID 36894987, 2023). "Eosinophils are involved in type II immune response, which is related to T helper 2 cells and various interleukins (including IL-4, IL-5, IL-9, IL-13, IL-31, and IL-33, among others), differing from the IL-17/23 axis of psoriasis." (PMID 36865550, 2023). "Several studies have pointed out that IL-33 is significantly increased at the lesion site and in the serum of psoriasis patients." (PMID 38239345, 2023). "Together, these data suggest that IL-33 partially mediates the exacerbating effect of MCs on psoriasis." (PMID 36894987, 2023). "Here, we outline recent findings on the mechanisms regulating IL-33 and IL-37 expression in AD and psoriasis." (PMID 37834081, 2023). "In WT mice, IL-33 significantly exacerbated IMQ-induced psoriasis-like dermatitis compared to the control mice." (PMID 36894987, 2023). "It has been reported that serum levels of IL-33 were significantly increased in conditions such as psoriasis, psoriatic arthritis and pustular psoriasis, and related to TNF-α." (PMID 36498859, 2022). "IL-33 also appears to be involved in the pathogenesis of psoriasis, participating in the crosstalk between innate and adaptive responses." (PMID 36012744, 2022). "Accordingly, we have shown that tapinarof and GFF, which act on AHR, increased the expression of IL-37, which in turn suppressed the expression of IL-33, a crucial cytokine in the development of AD and psoriasis." (PMID 35663970, 2022). "We found that the AHR-mediated IL-37 upregulation attenuates IL-33 expression which is one of the critical cytokines responsible for AD and psoriasis." (PMID 35663970, 2022).
psoriasis (continued). "Increased IL-33 serum levels have been found in patients with psoriasis, and they were significantly reduced after treatment with TNF inhibitors." (PMID 36012744, 2022). "In this article, we show for the first time the interrelationships between mast cells, cytokines IL-1, IL-33, and IL-36, and inflammatory states in psoriasis." (PMID 34360845, 2021). "Several studies showed that IL-33 not only played a role in the development of psoriasis but also participated in the progress of PsA." (PMID 34589505, 2021). "The recently discovered IL-33/ST2 signaling pathway has been linked to a wide variety of inflammatory skin disorders, including psoriasis and atopic dermatitis." (PMID 34884710, 2021). "Paradoxically, while psoriasis is considered as a Th1 and Th17 immunological disorder, there are some reports suggesting the pro-inflammatory contribution of IL-33 to this skin disease." (PMID 34884710, 2021). "Given the recognized involvement of IL-33 in psoriasis, the immunosuppressive activity of vitamin D and its therapeutic role in psoriasis, in the present study we investigated the effects of vitamin D on the expression of IL-33 and its receptor (ST2)." (PMID 34884710, 2021). "One of the newest studies, one showed that intradermal injection of recombinant IL-33 alone can induce psoriasis-like dermatitis through the transcriptional upregulation of such genes as IL-17, TNF, and other pro-inflammatory chemokines." (PMID 34884710, 2021). "MCs, through the production of IL-33, intervene in metabolic homeostasis, and in various diseases of the central nervous system—including stress, which exacerbates psoriasis." (PMID 34360845, 2021). "Our data indicated that vitamin D can modulate IL-33 signaling, opening up new perspectives for our understanding of the mechanism of vitamin D action in psoriasis therapy." (PMID 34884710, 2021). "In further studies, the same authors showed that IL-17A strongly upregulates the expression of IL-33 in the NHEK cells, suggesting involvement of IL-33 in the pathophysiology of psoriasis." (PMID 34884710, 2021). "There are a few reports describing an increased secretion of IL-33 by psoriatic keratinocytes and its pro-inflammatory role in psoriasis." (PMID 34884710, 2021). "These contradictory findings suggest that more research deeply focused on the immunopathology of IL-33 in psoriasis is needed." (PMID 32377165, 2020). "According to this, a review was performed to analyze if IL-33 even interplay in the onset of psoriasis, a Th1/Th17 inflammatory disease." (PMID 31736655, 2019). "The morphology of IL-23-injected skin is similar to lesional skin of human psoriasis; therefore, we used an IL-23 ear injection model to estimate the effect of IL-33 overexpression during skin inflammation." (PMID 28702024, 2017). "In this study, we investigated the impact of IL-33 deficiency in two models of chronic inflammation, namely CIA in C57BL/6 mice and IMQ-induced psoriasis in mice." (PMID 27317338, 2016). "In psoriasis, TNFα regulates IL-33, which promotes inflammation through mast and keratinocyte activation." (PMID 28042206, 2016). "Additionally, IL-32, IL-33, and IL-36α levels are increased in both the plasma and lesional skin of patients with psoriasis." (PMID 40731810, 2025). "Furthermore, both necroptosis and ferroptosis in keratinocytes have been implicated in psoriasis and IMQ-induced psoriasis-like dermatitis, through the release of inflammatory cytokines such as S100A8, S100A9, HMGB1, IL-33, IL-1β, and IL-6." (PMID 38429278, 2024). "However, IL-33 has been found to directly stimulate nerves in psoriasis, confirming that it is involved in the induction of pruritis." (PMID 38666958, 2024). "Interestingly, TNFα, INFγ and IL-17A, which are the main effectors of the Th1/Th17 response in psoriasis pathogenesis, were also found to stimulate the release of IL-33." (PMID 37509136, 2023).
psoriasis (continued). "As we have shown, IL-33 and IL-37 are highly expressed in the epidermis of AD and psoriasis." (PMID 37834081, 2023). "Since IL-33 induces a Th2 immune-deviated response via ILC2, IL-33 may be pathologically relevant in a population of Th17 plus Th2 cells involved in the immune response in psoriasis patients." (PMID 37834081, 2023). "Thus, keratinocyte-derived IL-33 contributes to the pathogenesis of psoriasis by promoting the maturation and differentiation of Th17 cells by dendritic cells and the infiltration of neutrophils and IL-17-producing cells into the epidermis." (PMID 37834081, 2023). "Furthermore, Hashimoto and colleagues have detected a decrease in the mRNA expression levels of IL-22, IL-23 and IL-33 in a mouse model of psoriasis." (PMID 37631238, 2023). "The relevance of the IL-33/ST2 axis in psoriasis has been highlighted in several studies." (PMID 36894987, 2023). "Considering that MCs constitutively express IL-33R, IL-33 is a potent MC activator, and IL-33 has been shown to play a critical regulatory role in psoriasis, we hypothesised that IL-33 could promote activation of MCs and thus regulate psoriasis development." (PMID 36894987, 2023). "Here, we hypothesise that IL-33 released by keratinocytes in psoriasis may influence disease development through MC activation." (PMID 36894987, 2023). "As such, AHR-mediated regulation of the IL-33–IL-37 axis may lead to new therapeutic strategies for AD and psoriasis." (PMID 37834081, 2023). "IL-33 is a potent MCs activator that is actively secreted by keratinocytes in psoriasis." (PMID 36894987, 2023). "Still, the direct effect of Staphylococcus Aureus observed on the IL-33/IL-31 axis suggests that the findings observed in AD could also be extended to psoriasis." (PMID 37509136, 2023). "In addition, IL-33 levels in the serum of psoriasis patients are known to be higher than in healthy individuals, and IL-33 levels decrease when the skin lesions are relieved by the treatment of psoriasis." (PMID 37834081, 2023). "Taken together, our findings provide the first evidence that tapinarof and GFF could have potential to prevent IL-33-overexpressing disorders such as AD and psoriasis via the AHR/IL-37 axis." (PMID 35663970, 2022). "Furthermore, we found that the knockdown of IL-37 resulted in the upregulation of IL-33, an alarmin cytokine with crucial roles in the pathogenesis of AD and psoriasis." (PMID 35663970, 2022). "Recently, HSP90 and IL-33 were shown to be upregulated in psoriasis patients." (PMID 36142767, 2022). "Our findings also suggest that ST2, a receptor for IL-33, may be involved in psoriasis biology and is a potential target for vitamin D action." (PMID 34884710, 2021). "Our results seem to be contradictory because of the involvement of IL-33 in the development of psoriasis, though the induction of lymphocytes Th17 and IL17 secretion, was recently postulated; however, in our study, expression of IL-17 was decreased in primary human keratinocytes (HPEKp)." (PMID 34884710, 2021). "The research observing repressive LC3 and Beclin1 levels in the lesions of imiquimod-induced and IL-33 intraperitoneal injection psoriasis model mice that demonstrated the autophagy and apoptosis is suppressed, which, the results of autophagy, is consistent with our experimental results." (PMID 33532507, 2021). "In addition, we have shown that IL-33 administered in combination with SP strongly increases the gene expression of TNF in human mast cells in vitro—an effect that would also occur in psoriasis mediated by neurotransmitters." (PMID 34360845, 2021). "That observation may be explained by the fact that upon psoriasis inflammatory stimuli, keratinocytes actively release IL-33, which in turn acts on surrounding keratinocytes via an autocrine manner." (PMID 34884710, 2021).